PTPN6 (protein tyrosine phosphatase non-receptor type 6)
Diseases named in the same sentence as PTPN6 in open-access papers (continued):
Sharing a sentence is not in itself a finding about the gene and the disease.
tumor (continued). "PTPN6 codes for the protein SHP-1 (protein tyrosine phosphatase, non-receptor type 6), a protein tyrosine phosphatase that is a putative tumor suppressor gene." (PMID 24704585, 2014). "Previous studies reported that several PTPs such as PTPN1, PTPN3, and PTPN6 have oncogenic properties but other PTPs including PTPN12 have tumor suppressor features." (PMID 22394684, 2012). "We verified the involvement of T-cell receptor signaling pathways in HNSCC as well as associated oncogenes such as LCK and PLCB1, and tumor suppressors such as STAT5A, PTPN6, PARK2." (PMID 21884569, 2011). "The findings of this study contribute to a better understanding of the role of PTPN6 in the tumor microenvironment and further demonstrate that PTPN6 may be a potential target for slowing the progression of MDS." (PMID 39590309, 2024). "Furthermore, PTPN6 is considered a candidate tumor suppressor gene in hematologic malignancies and solid tumors, mainly expressed in the hematopoietic system and epithelial cells, and is involved in regulating hematopoietic cell signaling." (PMID 39590309, 2024). "Furthermore, combining Ptpn6−/− OT-I T cell ACT with anti-PD-1 treatment resulted in superior control of tumours expressing low-affinity TAA compared to control ACT + PD-1 combinations." (PMID 38334623, 2024). "Furthermore, we found that PTPN6 blocked the penetration of CD8+ T cells into the tumor lesion while promoting the infiltration of Th17 cells and immunosuppressive cells, such as Tregs and M2 macrophages, into tumors." (PMID 37737713, 2023). "Moreover, the expression level of PTPN6 is related to malignant phenotypes such as malignant degree, invasion, and metastasis of tumors and plays a role of tumor suppressor genes in the development of tumors." (PMID 35186080, 2022). "However, deletion of PTPN6 significantly strengthens the capacity of these immune cells for tumor killing and promotes anti-tumor immunity." (PMID 35957898, 2022). "And the ability of tumor-associated DCs (TADCs) and MoDCs to take up and process immune complexes (IC) containing tumor antigens bound to antitumor antibody, ultimately inducing anti-tumor immunity in vivo, was augmented by simultaneous inhibition of PTPN6 and phosphatases regulating AKT activation." (PMID 35957898, 2022). "PTPN6 is thought to be a signaling molecule that can regulate many of cellular processes, including cell growth, differentiation, oncogenic transformation and mitotic cycle, as well as can act as a tumor suppressor." (PMID 34512722, 2021). "Therefore, we further analyzed the relationship between PTPN6 and immune cell infiltration in the tumor environment." (PMID 32454905, 2020). "Finally, Tumor Immune Estimation Resource (TIMER) was applied to investigate the relationship between PTPN6 and immune cell infiltration in the tumor microenvironment." (PMID 32454905, 2020). "It is attractive to hypothesize that the anti-tumor immunity observed in mice with inducible Ptpn6 deletion is due in part to enhanced T cell priming by DCs and increased effector T cell activity." (PMID 33133093, 2020). "We hypothesized that genomic amplification could contribute to the observed correlation between PTPN6 and pri-miR-200c-141 transcription levels in these tumours." (PMID 26725650, 2016). "Additionally, we discovered a significant relationship between PTPN6 gene expressions and microsatellite instability (MSI) and tumor mutation burden (TMB) in several cancer types, indicating that PTPN6 may have potential immunogenicity in these cancers." (PMID 37737713, 2023). "Moreover, we discovered that PTPN6 regulated tumor progression by reducing immune cell infiltration and inhibiting immune response, indicating that PTPN6 could be a therapeutic target for cancer immunotherapy in GBM." (PMID 37737713, 2023). "Therefore, PTPN6 can influence the prognosis of BC patients by regulating a variety of cancer-related signaling pathways and remodeling the immune microenvironment of a tumor." (PMID 32454905, 2020).
tumor (continued). "The inhibition of PTPN6 can potentially augment the infiltration of CD8+ T cells, enhancing the anti-tumor immune response and subsequently improving the clinical prognosis of GBM patients." (PMID 40270974, 2025). "In the context of tumor immunity, PTPN family members (PTPN6, PTPN3, PTPN2, PTPN1) shape the tumor microenvironment by regulating the development and function of immune cells, thereby influencing tumor progression and the efficacy of immunotherapy." (PMID 40570022, 2025). "The deletion of PTPN6, using CRISPR-Cas9 technology, has been reported to enhance the cytolytic capacity of CD133-targeting CAR-T cells in vitro and anti-tumour activity in vivo." (PMID 38334623, 2024). "Previous studies have found that promoter methylation of the PTPN6 gene leads to its low expression in MDS patients, where it is considered a tumor suppressor gene." (PMID 39590309, 2024). "TRIM26, PTPN6 (a cytoplasmic phosphatase), and BEX1 play critical roles in tumor immune inflammation." (PMID 38814177, 2024). "We evaluated the influence of PTPN6 expression on CD8+ T cell exhaustion, immune suppression, and tumor growth in human GBM samples and mouse models." (PMID 37737713, 2023). "Among these, it was found that the three PTPs PTPN6, PTPN11 and PTPRO both induce drug resistance and alter inflammatory cytokine regulation, and these molecules can influence tumor growth and HCC progression." (PMID 36660927, 2023). "Hypermethylation in the promoter region of PTPN6, the gene for the SHP-1 protein, is a representative epigenetic regulation mechanism that suppresses the expression of SHP-1 in tumor cells." (PMID 38203502, 2023). "Tyrosine-protein phosphatase non-receptor type 6 (PTPN6), also called protein tyrosine phosphatase-1 (SHP-1), was discovered to serve as an anti-tumor gene in lung cancer." (PMID 37279937, 2023). "The HR < 1 downregulation of PTPN6 and IKZF3 is considered a tumor suppressor, while the HR > 1 upregulation of HDLBP and EMC1 is considered an oncogene." (PMID 36211821, 2022). "The results indicated that compared with the control (si-NC), the silence of PTPN6 and PSMB8 significantly suppressed cell growth (p < 0.05), and the formation of tumor cell colonies (p < 0.01)." (PMID 35127714, 2021). "We found that numerous NK cell effector function-related genes, such as TBX21, FYN, NCR1, SH2D1A, SH2D1B, PTPN6, and IL18RAP, were downregulated in tumor-infiltrating NK cells." (PMID 34535671, 2021). "The results indicated that AIFM3, HSH2D, and PTPN6 were significantly up-regulated, while DCHS1, PTGIS, FLRT2, PCSK5, and CLSTN2 were significantly down-regulated in tumor samples compared with normal samples." (PMID 34512722, 2021). "We estimated the relationship between the abundance of six types of tumor-infiltrating immune cells (B cells, CD4+ T cells, CD8+ T cells, neutrophils, macrophages, and dendritic cells) and PTPN6 expression values in BC." (PMID 32454905, 2020). "Several key proteins such as MAP2K1, ITGB4, ITGA6, PTPN6, FMNL1, ANXA1, and MMP9 that modulate cell motility and tumor cell invasion were upregulated in MIBUC." (PMID 32326232, 2020). "Using a cohort of primary tumor tissues from PTCL patient data set we have analyzed the prognostic significance of pSTAT3 and PTPN6 expression for a broad spectrum of PTCLs." (PMID 30420593, 2018). "We identified 42 and 16 TSGs monoallelically deleted in P2 and P5, respectively, including several TSGs deleted in both tumor samples (ARHGEF10, CDKN1B, ETNK1, ETV6, LEPROTL1, NRG1, PTPN6, and WRN) and many TSGs co-deleted in the same subclone as well as across multiple subclones." (PMID 38658552, 2024). "Although the interaction between SHP-1/SHP-2 and PD-1 is thought to contribute to T cell exhaustion, the CD4cre Ptpn6/11fl/fl mice do not improve T cell-mediated tumor control." (PMID 38203502, 2023).
tumor (continued). "The tumor suppressive role of SHP-1, encoded by PTPN6 gene, has been made clear by reports of its negative regulation of several key oncogenic tyrosine kinases such as the JAK kinases and STAT3." (PMID 35941532, 2022). "In vivo data show that neither sustained nor acute Ptpn6/11 deletion improves T cell‐mediated tumor control." (PMID 36194675, 2022). "We analyzed the expression levels of PTPNs in the TCGA database and discovered that PTPN1, PTPN6, PTPN7, PTPN18, PTPN20, and PTPN22 were significantly upregulated in tumor samples, while PTPN4, PTPN5, PTPN10, PTPN11, PTPN13, PTPN14, and PTPN21 were downregulated in tumor samples." (PMID 36226189, 2022). "PTPN6, possessing an SH2 domain, was a tumor suppressor by dephosphorylation in CML." (PMID 34295818, 2021). "PTPN6 is a nonreceptor protein tyrosine phosphatase that can act as a tumor suppressor by dephosphorylating oncogenic kinases." (PMID 32454905, 2020). "Applying a systematic functional data assessment, we found various alterations including known hotspot mutations and one interesting PTPN6 mutation in the BCR, without the need of non-tumor DNA sequencing." (PMID 26053404, 2015). "Src homology-2-containing protein-tyrosine phosphatase 1 (SHP-1), also known as protein-tyrosine phosphatase non-receptor type 6 (PTPN6), is a candidate tumor suppressor that counteracts the action of tyrosine kinases, which play central roles in growth factor signal transduction." (PMID 41153438, 2025). "Furthermore, PTPN3, PTPN6, PTPN12 and PTPN13 play tumor suppressor roles in lung cancer." (PMID 35957898, 2022). "Negative correlation of STAT3 and PTPN6 in PTCL tumor samples was also analyzed by IHC (n = 146)." (PMID 30420593, 2018). "Furthermore, in zebrafish embryos, the lack of the PTPN6 gene results in an overactivated innate immune system and impaired ability to fight off bacterial infections, suggesting its role in inhibiting immune responses and enhancing tumor progression in GBM." (PMID 37737713, 2023). "GATA3, FOXA1, RASSF5, PTPN6, and TRNP1, involved in the luminal markers and negative regulation of cell proliferation, are related to tumor suppression and chemotherapy resistance." (PMID 36344487, 2022). "Overall, these results suggest a trend of negative correlation between PTPN6 and pSTAT3 in PTCL tumor samples." (PMID 30420593, 2018). "A further factor to consider is that PTPN6 recruitment to CAR cytosolic signalling domains appears to selectively impede T cell inflammatory cytokine production, and thereby reduce the incidence of cytokine release syndrome without impeding anti-tumour activity." (PMID 38334623, 2024).
cancer (38 papers, 2010 to 2025). A tumor composed of atypical neoplastic, often pleomorphic cells that invade other tissues. "To investigate the potential utility of PTPN6 as a novel immune target in pan-cancer, we analyzed the association between PTPN6 expression and immunotherapy response as well as drug sensitivity." (PMID 37737713, 2023). "To comprehensively explore the association between PTPN6 and cancer progression, we performed a Spearman correlation analysis between PTPN6 expression and cancer hallmark pathways in each cancer type." (PMID 37737713, 2023). "PTPN6 genetic alterations, including mutations, fusion, amplification, deep deletion and multiple alterations, are found in several types of cancer." (PMID 32596156, 2020). "GSEA showed that multiple cancer-associated signaling pathways are differentially enriched in the PTPN6 high expression phenotype." (PMID 32454905, 2020). "Dysfunction in PTPN6 regulation can cause abnormal cell proliferation and induce different kinds of cancers." (PMID 22216095, 2011). "Interestingly, five genes (CD247, CD3E, ZAP70, LCK, PTPN6) were associated with the hsa05235 pathway (PD-L1 expression and PD-1 checkpoint pathway in cancer)." (PMID 34880861, 2021). "Of note, allosteric PTPN11 inhibitors have shown high specificity over the related PTPN6 whilst retaining anti-cancer effects in pre-clinical studies and early-stage clinical trials." (PMID 38334623, 2024). "We also conducted an integrative analysis of PTPN6 and response to anti-cancer therapies in TCGA patients." (PMID 37737713, 2023). "We first investigated the PTPN6 gene expression in different cancer types using TCGA and GTEx databases." (PMID 37737713, 2023). "PTPN6 participates in various pathway regulations and is conceivable as a drug target in some types of cancer." (PMID 37737713, 2023). "PTPN6 can also increase the effect of chemotherapeutic drugs by binding to blocking antibodies in cancer immunotherapy." (PMID 36211821, 2022). "IL11, PTPN6 and CISH were significantly associated with survival outcomes in patients from 9 cancer cohorts." (PMID 31684858, 2019). "Silencing of PTPN6 gene expression in cancer cells due to DNA methylation in promiter via DNA methyltransferases 1 (DNMT1) has been widely described." (PMID 30420593, 2018). "PTPN6 participates in several cancer related pathways, including adherens junction, T cell receptor signaling pathway, B cell receptor signaling pathway, and Jak-STAT signaling pathway." (PMID 28938536, 2017). "Lastly, our method not only identified the known cancer genes but also detected the potential rare drivers (PTPN6 in THCA, SRC, GRB2 and PTPN6 in KIRC, MAPK1 and SMAD2 in HNSC)." (PMID 28938536, 2017). "Taken together these results indicate that PTPN6 mutations, N225K or A550V can deregulate STAT3 phosphorylation in cancer cells." (PMID 26565811, 2015). "Accordingly, SHP-1 was undetectable in CAF from multiple carcinoma origins compared with three primary hDF and regions 1 and 2 of PTPN6 promoter 1 of human CAF were hypermethylated compared with the hDF PTPN6 promoter." (PMID 26667266, 2015). "Extensive studies on PTPN6 revealed that the expression of PTPN6 was diminished or abolished in most cancer cell lines and tissues examined." (PMID 22216095, 2011). "Specifically, PTPN6 and PTPN11 are involved in the phosphoinositide 3 kinase/AKT/mammalian target of rapamycin (PI3K/AKT/mTOR) signaling pathway, which has been implicated in cancer progression and metastasis." (PMID 40806280, 2025). "A number of studies have addressed the question of whether and how PTPN6 influences T cell responses in cancer." (PMID 38334623, 2024). "In addition, the downstream annotation for the target gene showed that PTPN6 was associated with the prognosis of KIRC and was also overexpressed in most other cancer types." (PMID 36477791, 2023). "Other studies have shown that targeting PTPN6 may be an attractive therapeutic method for increasing the ability of leukocytes to fight cancer." (PMID 37737713, 2023).
cancer (continued). "Furthermore, protein tyrosine phosphatase non-receptor type 6 (PTPN6) was found to be a negative regulator of the inflammatory cell death pathways that take part in cancer immunity." (PMID 37214475, 2023). "Interestingly, PTPN6 was significantly overexpressed in most cancer types, including GBM and LGG, while significantly downregulated in LUAD, LUSC, and THYM." (PMID 37737713, 2023). "Moreover, PTPN6 can enhance the efficacy of chemotherapeutic and can combine with blocking antibodies in cancer immunotherapy." (PMID 32454905, 2020). "Beyond JAK3-mediated STAT3 phosphorylation, epigenetic silencing of negative regulators such as PTPN6 may contribute towards sustained STAT3 phosphorylation in cancer cells." (PMID 30420593, 2018). "Furthermore, studies showed that PTPN6 was a cancer marker gene closely related to DNA methylation." (PMID 36477791, 2023). "Then, the correlation between CNV and survival time of patients in the pan-cancer was evaluated, which suggested that the most effective gene of LIHC was PTPN6." (PMID 37884566, 2023). "We found that PTPN6 expression was positively correlated with PDCD1, CD274, CTLA4, LAG3, HAVCR2, and CD244 in most cancer types in TCGA, including LGG and GBM." (PMID 37737713, 2023). "The expression of genes in NPC tissues and normal tissues was observed, and it was found that the expression of BTK, CD72, PTPN6, and VAV1 was different in cancer and normal tissues, and the expression was lower in both cancer and normal tissues." (PMID 35957889, 2022). "As another example, miR-200c-3p was only strongly coexpressed with its host PTPN6 in OV by readthrough transcription (r = 0.57 and FDR < 0.01), while their expression was uncorrelated in most cancer types and was even inversely correlated in TGCT." (PMID 34572448, 2021). "Among the cell types that promoted T cell rejection, both cancer associated fibroblasts (CAFs) and myeloid-derived suppressor cells (MDSC) had significant negative correlations with PTPN6 expression." (PMID 37884566, 2023). "To assess the potential responsiveness of PTPN6 to anti-cancer drugs, we evaluated the correlation between PTPN6 expression and drug sensitivity for 252 anti-cancer drugs using the GDSC dataset across 1,074 cancer cell lines." (PMID 37737713, 2023). "According to our analysis of the TCGA database, cancer patients with PTPN6 genetic alteration(s) have a worse overall survival compared to those without PTPN6 alteration(s)." (PMID 32596156, 2020). "We then asked if STAT3 de-phosphorylation by 5-AZA could correlate with the upregulation of SOCS3 and/or PTPN6, as the former is a JAK/STAT inhibitor and the latter is a tyrosine phosphatase whose promoter methylation has been shown to contribute to STAT3 activation in other cancers." (PMID 38534772, 2024).
infection (6 papers, 2011 to 2024). The state of being infected such as from the introduction of a foreign agent such as serum, vaccine, antigenic substance or organism. "As expected, silencing Mlxipl effectively down‐regulated the expression of its target genes including Fasn, Acaca, Elovl6, Scd1, Ptpn6 and Pnpla3 at 36 hours after Ad‐siMlxipl infection although their expression was restored to the control level at 72 hours." (PMID 31809000, 2020). "Transcriptional profiling of Ptpn6-depleted animals showed elevated levels of pro-inflammatory cytokines and pathogen-recognition molecules that were further potentiated by infection." (PMID 24973748, 2014). "Depletion of the tyrosine-protein phosphatase Ptpn6 leads to hyperinflammation in zebrafish and exacerbated infection with both M. marinum and Salmonella typhimurium." (PMID 24973748, 2014). "Analysis of PTPN6 (ID 116689) expression on the mRNA level showed an increase by the infection and a reduction by dex in infected animals." (PMID 21412436, 2011). "PTPN6 was upregulated by the infection and downregulated by dex in the hippocampus of infected animals." (PMID 21412436, 2011). "Likewise, B cell differentiation genes (BCL10, CD72, FOS, PTPRC, SH3BP5, PTPN6, etc.)were also downregulated throughout the infection, correlating with the drop of B cell numbers at D8." (PMID 37146079, 2023).
bacterial infections (3 papers, 2010 to 2025). "Lyn, Itk, Was, Ptpn6, and Jun expression was downregulated, implying that the TCR signaling pathway may be suppressed in the early period (24 h) following bacterial infection." (PMID 20858287, 2010).
blood disorders (2 papers, 2015 to 2025). "Furthermore, four genes–UQCRFS1, PTPN6, RALY and ZMYM4–were identified for their associations with traits such as aging, forebrain and nervous system morphology, lung and bone morphology, neurodegenerative diseases and blood disorders." (PMID 40656995, 2025).